FOXO1 (forkhead box O1)
Diseases named in the same sentence as FOXO1 in open-access papers (continued):
Sharing a sentence is not in itself a finding about the gene and the disease.
breast carcinoma (continued). "FOXO1, SERPINB5, and STARD10 are putative breast cancer suppressor." (PMID 28793339, 2017). "In general, more aggressive breast cancers (MDA-MB-231, SUM159PT, BCCL2, BCCL3) had lower levels of TMX1 and SOD1 relative to the luminal MCF-7 cells, and showed up-regulated expression of TMX3, Foxo1, GSS and SOD2." (PMID 22479642, 2012). "Therefore, our results suggested that adipocytes might modulate the FOXO1/miR-135b/ circCNIH4 axis, thus enhancing the malignancy of breast cancer by inducing EMT and regulating copper homeostasis in breast cancer cells." (PMID 39135158, 2024). "Altogether, these observations suggest that FOXO3 protein, but not FOXO1 protein, may act as a tumor suppressor in breast cancer." (PMID 32332845, 2020). "Although the functions of FOXO1 have not been fully elucidated, it has been shown to act as a tumor suppressor in various human cancers, including melanoma as well as prostate, bladder, and breast cancers." (PMID 31823759, 2019). "In contrast with FOXO1, FOXO3, and FOXO4, FOXO6 could therefore be an oncogene in breast cancer." (PMID 29484124, 2018). "Out of the eleven candidate target genes regulated by rs117245733, the FOXO1 gene is notable, as its expression in primary human endometrial stromal cells is regulated by ESR142 and it is a direct protein–protein interaction partner of ESR1 in breast cancer cells." (PMID 30194396, 2018). "Additionally, overexpression of SIRT1 with FOXO1 potentiated the transcription of multiresistance protein 2 (MRP2), and the basal activity and expression of SIRT1 was increased in tamoxifen-resistant breast cancer cells." (PMID 25569080, 2015). "For example, binding motifs for E2F and Fox family members, including FOXO1 (FOXO1A), FOXA1 (HNF3A), and FOXF2 (FREAC2,4), are highly enriched in PR-binding sites in breast cancer cells but not in leiomyoma cells." (PMID 22272226, 2012). "Importantly, we validated such a negative correlation between FOXO1 and AQP3 at the protein expression level using 55 breast cancer clinical samples, with the p value from the chi-squared test being 4.63E-20 and the correlation score being -0.54." (PMID 35637961, 2022). "Indeed, nuclear accumulation of FOXO1, but not that of other TFs, promotes SOX2 gene expression in breast cancer." (PMID 31844113, 2019).
diabetes (191 papers, 2007 to 2026). "Previously, a numberof polymorphic loci of FOXO1 have been shown tobe associated with type 2 diabetes mellitus and obesity." (PMID 41164273, 2025). "The results suggest that hucMSC‐derived exosomes ameliorate diabetes‐associated muscle atrophy by enhancing SIRT1/FoxO1/3a‐mediated mitochondrial function and that Apt conjugation strengthens the effects of MSC‐EXOs on muscle atrophy." (PMID 39871746, 2025). "Hussain S., Yadav S.S., Dwived.i P., Banerjee M., Usman K., Nath R.,Khattri S. SNPs of FOXO1 and their interactions contributes to theenhanced risk of diabetes among elderly individuals." (PMID 41164273, 2025). "Forkhead box transcription factor O1 (FOXO1) is associated with stress, apoptosis, glucose metabolism, angiogenesis, tumorigenesis, diabetes, and immune system diseases." (PMID 38405620, 2024). "Inhibition of FoxO1, 3 and 4 has been shown to completely arrest muscle loss in conditions such as fasting, hind limb suspension, immobilization, diabetes and glucocorticoid treatment." (PMID 38668315, 2024). "The mechanism is linked to the impact of diabetes on Foxo1-stimulated RANKL expression in chondrocytes and premature resorption of cartilage to reduce the anlagen for bone and callus formation." (PMID 37591875, 2023). "Upregulation of Foxo1 induced by diabetes increases osteoclast formation, premature loss of cartilage and impaired subsequent bone formation." (PMID 37591875, 2023). "For example, studies have shown that increased FoxO1 activity in certain tissue types contributes to T2D pathology, symptoms, and comorbidities, yet in other tissue types elevated FoxO1 has been reported to alleviate symptoms associated with diabetes." (PMID 37941908, 2023). "FOXO1 deletion rescues reduced callus formation caused by diabetes measured by microCT and histologically." (PMID 37576976, 2023). "Metabolic dysfunction associated with fatty liver disease and atherosclerosis is just some of the metabolic conditions that can lead to diabetes, obesity, or both, which are caused by FoxO1 pathway dysfunction." (PMID 36361416, 2022). "Mechanistically, diabetes causes FOXO1 to shed from the promoter region of growth factors (such as TGF-β and VEGF) and to bind to the promoter region of pro-inflammatory and pro-apoptotic genes." (PMID 36552853, 2022). "LINC01619 regulates miR-27a/FoxO1 (forkhead box protein O1) and ER stress-associated podocyte cell injury in diabetes." (PMID 34199672, 2021). "Simultaneously, it reversed diabetes-associated oxidative stress by activating AMPK-Akt to inhibit FOXO1 and recovering PDX-1 nuclear localization." (PMID 34335803, 2021). "Foxo1 is a member of ‘O’ class forkhead transcription factors and has been reported to be implicated in various diseases, such as diabetes, myocardial glucose oxidation and cancers." (PMID 33955666, 2021). "In advanced diabetes, FoxO1 disappears from β cells, accompanied with the loss of insulin signaling." (PMID 34727995, 2021). "Taken together, our data suggest that FoxO1 is a critical trigger for type 1 diabetes‐induced vascular remodelling in rats, and inhibition of FoxO1 thus offers a potential therapeutic option for diabetes‐associated cardiovascular diseases." (PMID 33108705, 2020). "In diabetes, the cardiac energy flexibility (shift fuel preference) is constrained, which was demonstrated to be associated with aberrantly active myocardial FOXO1." (PMID 32450616, 2020). "We discovered that diabetes increases FoxO1 protein level in rat carotid arteries and the increase in FoxO1 protein is associated with vascular remodelling." (PMID 33108705, 2020). "Mutations in HDAC4 disrupt the deacetylation of FoxO1, subsequently decrease the β‐cell function including insulin secretion, resulting in diabetes." (PMID 30968599, 2019).
diabetes (continued). "Foxo1 and Foxo4 upregulation was implicated in diabetes, diabetic complications and cardiovascular disease, through impairing proliferation and differentiation, and abnormal cytokine expression, inflammation, and resistance to oxidative stress." (PMID 29995913, 2018). "Suppression of PPARγ activity is further intensified by JNK (c-Jun N-terminal kinase) activation via diabetes associated oxidative stress which facilitates nuclear localization and activation of FOXO1 in adipocytes." (PMID 30376839, 2018). "In diabetes, the activated FoxO1 was associated with the dysregulation of metabolic homeostasis and activation of cell death signaling." (PMID 30294283, 2018). "Simultaneously, diabetes associated oxidative stress also activated FOXO1 and triggered nuclear exclusion of PDX1 which resulted in β-cell dysfunction." (PMID 29093682, 2017). "FOXO1 seems to stimulate cell demise, particularly in tissues that are influenced by diabetes associated complications where oxidative stress is beyond normal limits." (PMID 26956801, 2016). "Moderate increment of FOXO1 expression in heart diminished while its cardiac overexpression in diabetes or deficiency aggravated myocardial ischemia reperfusion injury." (PMID 26956801, 2016). "This represents another paradox, as diabetes leads to greater activation of FOXO1 but this greater activation is associated with a reduced ability to stimulate TGF-β1 transcription." (PMID 25226535, 2014). "It has been proposed that diabetes-enhanced activation of FOXO1 is associated with several diabetic complications." (PMID 24864265, 2014). "Murine Foxo1 ablation caused elevated liver and plasma triglyceride levels, two signature lipid abnormalities of diabetes and the metabolic syndrome." (PMID 25506828, 2014). "In conclusion, we demonstrated that FoxO1 gain of function in the pancreas causes diabetes, polycystic pancreas, and islet hypervascularization." (PMID 22384192, 2012). "We showed that dysregulation of FoxO1 in pancreas causes diabetes, polycystic pancreas and islet hypervascularization." (PMID 22384192, 2012). "These include transcription factors concerned with the control of: adipogenesis (Pparγ, Klf15, Irf1, Creb1, Egr2, Gata3); lipogenesis (Mlxipl, Srebp1c); inflammation (Jun, Stat3); insulin signalling and diabetes susceptibility (Foxo1, Tcf7l2)." (PMID 21187013, 2010). "They demonstrated a significant reduction in blood glucose levels by introducing an inactive FoxO1 variant (FoxO1‐∆256) into the hepatic tissue of db/db mice (a common murine model for studying diabetes, obesity, and metabolic disorders, due to a mutation in the leptin receptor gene)." (PMID 39533662, 2025). "Although FABP4, FOXO1, and metformin have previously been implicated in metabolic regulation and inflammation, no study has attempted to establish a connection between these pathways in relation to diabetes-induced kidney aging." (PMID 41471323, 2025). "Local high levels of TNF-α could activate FOXO1 in the process of endochondral ossification in patients with fractures associated with diabetes, leading to an increased mRNA expression level of apoptosis gene and chondrocyte apoptosis." (PMID 38713402, 2024). "Studies have shown that FOXO1 is strongly associated with diabetes." (PMID 38405620, 2024). "FoxO1 deficiency may also contribute to β-cell senescence and T2D as knockout of the proliferation mediator SMAD7 reduced FoxO1 which enhanced β-cell ageing and caused diabetes suggesting that there may be an optimal range of FoxO1 activity." (PMID 37941908, 2023). "In conclusion, the decrease in insulin/Igf signaling induces Foxo1 and Gsk-3β function, resulting in impaired replication and enhanced β-cell death at transcription and protein levels, respectively, ultimately leading to postnatal β-cell loss and diabetes." (PMID 36361703, 2022).
diabetes (continued). "We revealed herein that 1,25D could attenuate bone loss through alleviating diabetes-mediated excessive autophagy via PI3K/Akt/FoxO1 signaling pathway." (PMID 33450223, 2021). "Together, our results suggest that the PI3K/Akt/FoxO1 signaling pathway is involved in the osteoprotective effect of 1,25D by attenuating autophagy in diabetes, providing a novel insight for the prevention and treatment of diabetes-caused bone loss." (PMID 33450223, 2021). "Based on our results, pharmacological targeting of the ERK3/MK5/FOXO1 pathway might be a valid strategy to treat obesity and associated diabetes." (PMID 32139423, 2020). "Thereby, we also analyzed whether any of the selected SNPs in FoxO1/FoxO3 is associated with gender, smoking, medical history of hypertension, diabetes mellitus, hyperlipidemia and MetS in our study population." (PMID 24489705, 2014). "Interestingly, in human beta cells, it has been shown recently that FOXO1 is a core component in adaptation to metabolic stress, and impaired FOXO1 activation would cause or exacerbate diabetes." (PMID 25299696, 2014). "Actually, Stat1 was over-expressed in Timp3−/− diabetic kidney compared to the WT; moreover, abolishing Stat1 expression by RNA interference caused a complete rescue of FoxO1 expression, suggesting a possible role of STAT1 in linking Timp3 deficiency to FoxO1 regulation." (PMID 23401241, 2013). "Therefore, it is intriguing that FoxO1 dysregulation in pancreatic cells causes both diabetes and pancreatic polycysts in TG mice." (PMID 22384192, 2012). "Moreover, high glucose and advanced glycation endproducts that are elevated in diabetes stimulate loss of microvascular retinal pericytes through a process that involves activation of FOXO1." (PMID 22454632, 2012). "However, the diminished mechanical strength caused by diabetes was significantly reversed by deletion of Foxo1 in osteoblasts, evidenced by the modulus of rigidity and maximum torque being restored to 87% and 100%, respectively to the points similar to NG controls." (PMID 37591875, 2023). "Interestingly, decreased circulating insulin in diabetes is associated with increased FoxO1 activation, whereas mitochondrial reactive oxygen species (ROS) production was enhanced by altering redox balance and impacting the activity of redox‐sensitive proteins, such as protein kinase C‐ε." (PMID 33108705, 2020). "Finally, low Sirt1 and Sirt3 expression, due to high NADH/NAD, may decrease Foxo-1 and MnSod expression, causing oxidative stress that results in cell death/aging or diabetes." (PMID 26558285, 2015). "However, it is still unclear whether FoxO1 dysregulation in the pancreas could be the cause of diabetes." (PMID 22384192, 2012). "Thus, the accumulated evidence suggests FoxO1 dysregulation in the pancreas could be the cause of diabetes or pancreatic disease." (PMID 22384192, 2012). "FoxO1 activity can be regulated through its mRNA and protein modifications, making it a therapeutic target for conditions like cancer, wound healing, and diabetes." (PMID 41362741, 2026). "Immunofluorescence results indicated an increase of FOXO1 nucleus accumulation in AVE 0991-treated diabetic cognitive impairment mice, suggesting the enhancement of FOXO1 transcriptional activity." (PMID 40303297, 2025). "Collectively, these outcomes point toward the potential role of QCT and SS in managing diabetes by modulating hepatic glucose production via the PI3K/Akt/FOXO1 pathway." (PMID 39846548, 2025). "Using a combination of in silico analyses, genetic cellular studies, pharmacological approaches, and cardiomyocyte-specific knockout mice, we demonstrate that the upregulation of zDHHC4 in diabetes is mediated by activation of the FoxO1 transcription factor." (PMID 40357580, 2025). "Targeting FoxO1‐dependent regulation of gluconeogenesis in the liver appeared to be a highly feasible approach for diabetes treatment." (PMID 39533662, 2025).
diabetes (continued). "The first in vivo study suggesting the relevance of FoxO1 inhibition in diabetes was published in 2003." (PMID 39533662, 2025). "Lastly, FOXO1 is seen to have potential involvement in diseases like esophageal adenocarcinomas, type 2 diabetes mellitus, Parkinson's disease, metabolic syndrome, cardiovascular diseases, aging, and stem-cell activity." (PMID 39844998, 2025). "SIRT1 reduces diabetes‐induced renal injury by synergistically working together through FOXO1‐mediated oxidative stress and autophagy." (PMID 40008520, 2025). "Activation of the FoxO1 transcription factor in diabetes upregulates the transcription of the S-acylating enzyme zDHHC4, driving increased CD36 S-acylation and membrane relocalization." (PMID 40357580, 2025). "The SIRT1/FOXO1 signalling pathway is involved in the regulation of a variety of physiological processes, and SIRT1 can play a synergistic role in attenuating diabetes‐induced renal injury through FOXO1‐mediated oxidative stress and autophagy together." (PMID 40008520, 2025). "In 2010, pilot studies of two small‐molecule inhibitors (AS1708727, AS1842856) initiated intensive preclinical research of FoxO1 in diabetes." (PMID 39533662, 2025). "The increased O-GlcNAcylation of FoxO1 was observed in diabetes, resulting in the activation of FoxO1 and regulating antioxidative stress in response to glucose metabolism." (PMID 38987770, 2024). "Inhibition of FoxO1 has shown positive effects on glucose homeostasis in experimental models of diabetes supporting its potential targeting." (PMID 39100099, 2024). "Another study also showed that hyperactivation of the PI3K/Akt/FoxO1/LOXL2 pathway promotes the development of myocardial fibrosis in the cardiomyocytes of patients with diabetes." (PMID 38883603, 2024). "Previous studies show an opportunity for novel therapies for diabetes mellitus and the relationship among FOXO1, gluconeogenesis, AMPK activation, PEPCK, G6Pase, and Akt." (PMID 39329975, 2024). "Taken together, these results suggest that LOXL2 plays an important role in myocardial fibrosis in diabetes, which occurs secondary to the high-glucose environment and is mediated through FoxO1." (PMID 38883603, 2024). "Apart from its roles in energy metabolism and oxidative stress, FoxO1 also has substantial roles in myocardial cell death via apoptosis and autophagy during diabetes." (PMID 39206323, 2024). "Conditional FOXO1 deletion in chondrocytes in diabetic animals resulted in a partial and significant rescue of diabetes-inhibited formation of small and moderate-sized blood vessels (P<0.05)." (PMID 37576976, 2023). "Deletion of Foxo1 in the liver of L-DKO mice and db/db mice led to a reduction of gluconeogenesis and diabetes amelioration, whilst Foxo1 deletion in the hearts of high-fat diet (HFD) mice prevented heart failure." (PMID 36831004, 2023). "In summary, we report the discovery that CDK4 promotes insulin signaling and FOXO1 degradation in the pancreatic β cell, derepressing Pdx1 expression and rescuing diabetes in Irs2–/– mice." (PMID 37712417, 2023). "During IR and diabetes development, due to IRS loss and the inactivation of the PI3K → Akt signaling pathway, the Foxo1 inhibitory mechanism is uncontrolled, due to Akt activation during feeding and/or insulin stimulation." (PMID 36831004, 2023). "The present study clearly shows that vitamins C and E have the potential to control GSK 3β and FOXO1 gene-mediated diabetes mellitus in glyphosate-exposed animals." (PMID 38274944, 2023). "In this study, we found that diabetes impairs fracture healing through Foxo1-mediated transcriptional inhibition of IFT80 expression and disruption of primary cilia formation in osteoblasts, thereby resulting in impaired osteogenesis." (PMID 37591875, 2023). "Previous studies demonstrated that diabetes upregulates Foxo1 expression and activation and diabetes impairs ciliogenesis resulting in defective fracture repair." (PMID 37591875, 2023).